LAG3 (lymphocyte activating 3)
Diseases named in the same sentence as LAG3 in open-access papers (continued):
Sharing a sentence is not in itself a finding about the gene and the disease.
tumor (continued). "Fourth, PIEZO1 shows positive associations with tumor microenvironment scores (Stromal/Immune/ESTIMATE) and immune checkpoint markers (CD274, CTLA4, LAG3, PDCD1, PDCD1LG2)." (PMID 40977743, 2025). "After 3 days of coincubation, we measured tumor killing by annexin staining of EPCAM+ tumor cells, and exhaustion was measured by LAG3, PD-1, TIM3, and CD39 expression on CD8+ T cells." (PMID 40459946, 2025). "In vivo experiments demonstrated that blocking LAG-3 with specific antibodies retards tumor growth by enhancing CD8+ T cell-mediated anti-tumor responses and reducing immunosuppressive cell populations." (PMID 40805285, 2025). "Co-blockade of LAG-3 and PD-1 has demonstrated enhanced anti-tumor immune responses in preclinical and clinical settings." (PMID 40787471, 2025). "In particular, LAG3-high NK cells are found in HIV-infected individuals, as well as in tumor diseases, which is associated with a poor survival prognosis." (PMID 41369346, 2025). "They showed that NF1, TSC1, and TGF-β RII are important tumour suppressors that regulate immune composition, and their loss enhances IL6-JAK3-STAT3/6 inflammatory pathways, increasing LAG3 + CD8 and CD4 T cells." (PMID 40650785, 2025). "Within brain metastases, coexpression of checkpoint molecules such as PD-1, TIM-3, and LAG-3 on tumor-infiltrating lymphocytes is common and in many contexts reflects a state of terminal exhaustion often unresponsive to PD-1/PD-L1 blockade alone." (PMID 40943541, 2025). "Elevated LAG‐3 expression on CD8+ T lymphocytes has been observed in the tumor microenvironment of various solid tumors." (PMID 40091778, 2025). "LAG3 functions as a vital checkpoint receptor on immune cells, serving an essential purpose in controlling T cell activity and anti-tumor immunity." (PMID 41186850, 2025). "Recent research has shed light on the role of galectin‐3 as a ligand for lymphocyte activation gene‐3 (LAG3), which jointly affects T cell function with LAG3, thereby promoting immune escape of tumor cells." (PMID 39720765, 2025). "CRISPR-Cas9 is used to knockout immune checkpoint genes (e.g., PD-1, TIGIT, LAG-3) in T cells, enhancing their anti-tumor activity by overcoming immunosuppressive effects in the GBM microenvironment." (PMID 40223940, 2025). "T cell dysfunction in cancer is marked by the expression of multiple inhibitory receptors, such as LAG-3 and PD-1, on tumor-infiltrating lymphocytes (TILs)." (PMID 40076932, 2025). "LAG‐3, another critical target molecule, has emerged as a key target for immune checkpoint inhibitors in tumor immunotherapy." (PMID 40091778, 2025). "Tumor cells secrete immunosuppressive cytokines, such as interleukin-10 (IL-10), prostaglandin E2, and lymphocyte-activation gene 3 (LAG-3), thereby promoting immune evasion." (PMID 41229433, 2025). "The dual inhibition of PD-L1 and LAG-3 using the BsAb IBI323 enhances T-cell-mediated anti-tumor responses beyond the efficacy of monotherapies or combination therapies, indicating a synergistic mechanism of immune activation." (PMID 41239350, 2025). "Upregulation of PD-1 and LAG-3 is indicative of T cell exhaustion, leading to increased tolerance to self and tumour antigens and facilitating tumour immune evasion." (PMID 39901202, 2025). "The expression of LAG3 has been found to be upregulated after MWA, and an experiment in a mouse model suggests that introducing LAG3 blockade into MWA delays tumor progression and prolongs survival." (PMID 40236647, 2025). "Forty-five pretreatment tumor specimens (37 archival, 8 freshly collected) were analyzed for PD-L1, LAG-3, and MHC II expression." (PMID 40234667, 2025). "In part 2A, 38% (n = 13) of patients had LAG-3 positive tumours while in part 2B, 58% (n = 14) of patients had LAG-3 positive tumours." (PMID 40016550, 2025). "Future research should expand sample sizes and conduct cross‐tumor comparative studies to elucidate the toxicity of LAG‐3 inhibitors." (PMID 40787068, 2025).
tumor (continued). "We found that CX-5461 significantly sensitized CT26 tumours to anti-Lag3 immunotherapy, leading to potent tumour regression." (PMID 40646287, 2025). "Based on human single-cell data from BCBM and liver metastases, alternative immune checkpoints such as LAG3–galectin-3 are highly active in tumor and infiltrating cells, suggesting their potential as important complements to PD-1/PD-L1 inhibitors." (PMID 41219968, 2025). "LAG-3 is highly co-expressed with PD-1 in tumor-infiltrating CD4+ and CD8+ T lymphocytes, and dual inhibition of LAG-3 and PD-1 has demonstrated synergistic antitumor activity in preclinical studies." (PMID 39751894, 2025). "For example, the combination of LAG-3 and PD-1 inhibition has shown notable efficacy across various tumor models." (PMID 40356928, 2025). "The authors first interrogated LAG3 expression on T cells across murine tumor models, classifying the models as LAG3hi or LAG3lo." (PMID 40517319, 2025). "Meanwhile, the top three genes that are least correlated with KLF4 and associated with a tumor inhibitory effect in several tumors were BTLA, IDO1, and LAG3." (PMID 40299916, 2025). "Lymphocyte activation gene 3 (LAG3) is an additional inhibitory receptor associated with cellular immune regulation and tumor immune evasion." (PMID 39858107, 2025). "Nevertheless, the release of Gal-3, an alternative ligand for LAG-3, by CSCs was found to induce T cell apoptosis and suppress anti-tumor immunity." (PMID 41233805, 2025). "This reduced PD-1+LAG3+TIGIT+ phenotype was maintained after subsequent re-challenges with ACHN tumor cells." (PMID 40519930, 2025). "Remarkably, CD8+ T cells within the tumor functioned better when the PD-1 and LAG-3 signaling pathways were blocked, which resulted in more interferon-γ (IFN-γ) and IL-2 production." (PMID 41357215, 2025). "In summary, immune checkpoint molecules such as TIGIT, LAG-3, and PD-1 hold significant promise for application in tumor immunotherapy." (PMID 40809844, 2025). "LAG-3 expression is often upregulated in tumor-infiltrating lymphocytes (TILs) of patients treated with anti-PD-1 mAbs." (PMID 40796887, 2025). "Several studies have shown that compared with monotherapy, the combination therapy of TIM3 or LAG3 inhibitors with PD-1 blockade therapy can significantly enhance anti-tumor activity, and patients have good tolerance to the combination therapy." (PMID 40087690, 2025). "The results showed that all novel tribodies induced a more potent tumor cytotoxicity than the combination of 53 P with each immunomodulatory bi-specific targeting PD-L1 or PD-1 and LAG-3." (PMID 39929828, 2025). "In mouse model experiments, knockout of the LAG3 gene rendered NK cells unable to kill specific tumor targets." (PMID 40298450, 2025). "In our study, a higher expression of the ICP molecule CD276 was shown in the tumor tissue, particularly in WLWH - IS, which was associated with increased expression of T cell exhaustion markers CTLA4 and LAG3 in different T cell subpopulations." (PMID 40393975, 2025). "They further showed that LAG3 and PD-L1 targeting therapies inhibit metastasis in NF1-, TSC1-, or TGF-β RII-deficient tumours." (PMID 40650785, 2025). "We also discovered that LAG3 + T cells stayed away from tumor cells after treatment, particularly LAG3 + CD4 + T cells, whose changes of minimum distance to tumor cells were statistically significant (31.01 μm vs 42.98 μm, p = 0.023)." (PMID 40411616, 2025). "T cell exhaustion, a dysfunctional state marked by TOX-driven transcriptional reprogramming and sustained expression of inhibitory receptors (e.g., LAG-3, CTLA-4), is a hallmark of chronic viral infections and tumor microenvironments." (PMID 40830893, 2025). "Experiments have confirmed that LAG3 inhibits tumor progression by regulating Treg and CD8+ T cells, providing a new target for immunotherapy." (PMID 41025546, 2025).
tumor (continued). "The expression of LAG3, as well as other immune checkpoint molecules, is particularly strongly increased in tumor-infiltrating lymphocytes." (PMID 41369346, 2025). "Enhancing the proliferative and anti-tumor capabilities of effector T cells can be accomplished by targeting the elevated expression of LAG3 on CD8+ and CD4+ T cells in the bone marrow and blood of patients with multiple myeloma." (PMID 41019045, 2025). "FGL1 can negatively regulate the tumor immune microenvironment by inhibiting T cell activation through binding to LAG3." (PMID 41024301, 2025). "LAG-3 is another co-inhibitory receptor expressed on tumor-infiltrating lymphocytes and tumor cells, where it acts to suppress T cell proliferation and function." (PMID 40725830, 2025). "Future clinical trials should prioritize biomarker-driven patient selection (e.g., LAG-3 expression on tumor-infiltrating lymphocytes) and explore their roles in overcoming resistance to existing ICIs." (PMID 41463185, 2025). "Meanwhile, the level of immunosuppression factors in tumor tissues, such as LAG-3, CTLA-4, and IDO-1, increased significantly." (PMID 40487392, 2025). "Lymphocyte activation gene-3 (LAG3), an important inhibitory immune checkpoint in tumor immunity, is expressed on activated CD4 + and CD8 + effector and exhausted T cells, natural killer (NK) cells, and B cells induced by T cells." (PMID 40411616, 2025). "Single‐cell RNA sequencing data (GSE171894, GSE168652) were analyzed to explore LAG3 expression in the tumor immune microenvironment." (PMID 41025546, 2025). "miR-146 targets LAG-3 mRNA and downregulates its expression, alleviating T cell inhibition and enhancing anti-tumor immunity." (PMID 41019058, 2025). "In NRES, sPD1 and sLAG-3 showed a direct correlation and it is known that PD1 and LAG-3 are often co-expressed on both exhausted T cells and tumor cells within the tumor microenvironment." (PMID 39910579, 2025). "LAG-3 expression is evaluated in the context of diverse clinical settings and tumor microenvironmental factors." (PMID 40649775, 2025). "PD-1 and LAG-3 expression, as well as circulating tumor DNA (ctDNA) expression pre- and postoperatively, was a prognostic factor." (PMID 40277786, 2025). "As a result, inhibitory immune pathways and checkpoint molecules—such as PD-1, CTLA-4, TIM-3, and LAG-3—are often highly expressed on tumor-infiltrating lymphocytes, which further supports the development of an immunosuppressive tumor landscape." (PMID 41294877, 2025). "There are several additional inhibitory immune checkpoints that limit the antitumor response of activated T-cells within the tumor microenvironment, including the transmembrane glycoprotein PD-1 and LAG-3." (PMID 40108693, 2025). "Studies suggest that blocking TIM-3 can restore T-cell function, while LAG-3 inhibition synergizes with the PD-1 blockade to enhance anti-tumour responses." (PMID 41463180, 2025). "In this study, we performed SPECT/CT imaging of 99mTc‐HYNIC‐αLAG‐3 and 99mTc‐HYNIC‐αPD‐L1 to disclose the correlation between tracer tumor uptake and the expression levels of LAG‐3/PD‐L1." (PMID 39513410, 2025). "Dual targeting of LAG-3 and TIGIT or triple inhibition of LAG-3, PD-1, and Tim-3 reduces tumor growth." (PMID 40361336, 2025). "More recently, the combination of nivolumab (anti-PD-1) and relatlimab (anti-LAG-3) has demonstrated strong anti-tumour activity in the neoadjuvant treatment of dMMR CRC, with a pathological response rate of 97%." (PMID 40016550, 2025). "HLB-apt demonstrated specific binding capacity to both HER2-expressing tumor cells (A549 and HepG2) and LAG3-positive Jurkat cells." (PMID 40761795, 2025). "Within the tumor microenvironment, Gal-3, via LAG-3 expression, inhibits the activation of antigen-specific CD8+ T cells and suppresses the expansion of plasmacytoid DCs, thereby impeding the formation of an effective anti-tumor immune response." (PMID 40356928, 2025).
tumor (continued). "T-cell immunoglobulin and mucin-domain containing-3 (TIM-3) and lymphocyte-activation gene 3 (LAG-3) are emerging checkpoints involved in tumor-induced immune suppression." (PMID 40870970, 2025). "To date, the U.S. Food and Drug Administration has approved three classes of ICIs, targeting CTLA-4, PD-1/PD-L1, and LAG-3, with additional agents in development across over 20 tumor types in the neoadjuvant, adjuvant, and metastatic settings." (PMID 41228374, 2025). "[68Ga]Ga-NOTA-C25 PET imaging effectively and noninvasively detected LAG-3+ tumor-infiltrating lymphocytes (TILs) in Hepa1-6 tumor-bearing mice." (PMID 40796887, 2025). "Beyond the PD-1/PD-L1 axis, other immune checkpoints, such as TIM-3, CTLA-4, and LAG-3, have gained significant attention for their roles in tumor immunology." (PMID 40870970, 2025). "Our study demonstrated that LAG3 knockdown enhanced tumor proliferation and migration, while inhibiting E‐cadherin and activating cellular pyroptosis effectors." (PMID 41025546, 2025). "In the TME, high LAG-3 expression in immune cells correlates with their exhaustion and a reduced capacity to eliminate tumor cells." (PMID 40574024, 2025). "LAG-3 is expressed at higher levels on both effector and regulatory T cells within the tumor microenvironment." (PMID 41550427, 2025). "Nanostring gene expression analyses demonstrated that both ICIs increased the numbers of tumor-infiltrating lymphocytes (TILs), specifically cytotoxic cells (i.e. Mx1, anti-LAG-3 p < 0.01; anti-PD-L1 p < 0.0001 vs." (PMID 40674934, 2025). "Early results indicate that dual blockade of LAG-3 and PD-1 exhibits significant anti-tumor activity with manageable toxicity profiles, highlighting its potential as a novel immunotherapy approach for HCC." (PMID 40918452, 2025). "Current research on the TB‐associated tumor microenvironment focuses on the PD‐1/PD‐L1 axis; however, the expression patterns of other immune checkpoints, such as TIM‐3, LAG‐3, and TIGIT, and their relationship with T‐cell depletion, remain underexplored." (PMID 40347011, 2025). "Tumor-infiltrating Tregs expressed high levels of cell surface molecules associated with T-cell activation, such as CTLA4, PD-1, LAG3, TIGIT, ICOS, and TNF receptor superfamily members." (PMID 40092987, 2025). "Bavunalimab is a CTLA-4- and LAG3-targeting bispecific antibody developed to achieve anti-tumor effects by activating T cells." (PMID 41155207, 2025). "In terms of detailed inhibitory receptor expression analysis, significantly higher fractions of tumor-infiltrated CD4+ T cells expressed LAG-3 (13.06 ± 4.63% of CD4+ T cells) and PD-1 (14.01 ± 3.76% of CD4+ T cells)." (PMID 41221283, 2025). "For instance, a numerically higher progression-free survival (PFS) was observed in the phase III registrational study of relatlimab in combination with nivolumab for those tumor samples with LAG-3 overexpression assessed by immunohistochemistry." (PMID 40508202, 2025). "Significant correlations were observed between in vivo tumor uptake and ex vivo tumor uptake (R2 = 0.95, p < 0.001) as well as LAG‐3 expression level (R2 = 0.94, p < 0.01) in the Pearson correlation analyses." (PMID 39513410, 2025). "Taken together, our findings indicate that ribosome-targeting therapy remodels the TME, remarkably enhancing the anti-tumour effects of Lag3 blockade in immunologically cold tumours." (PMID 40646287, 2025). "LAG-3 expression is upregulated in tumor infiltrating CD8+ T cells in a variety of tumor types including HCC." (PMID 40076561, 2025). "As our study showed that a positive HPV tumor status is associated with an increased expression of the T cell exhaustion biomarkers PD-1, TIM-3, and LAG-3, our results provide a potential explanation for their observation." (PMID 39769271, 2024). "LAG3 contributes to tumor immunity by regulating methylation, influencing the production of immune-related cytokines, and promoting treatment resistance." (PMID 39839672, 2024).
tumor (continued). "On the one hand, the binding of LAG-3 to MHC-II affects anti-tumor immune responses by negatively regulating the activity of T cells." (PMID 39660130, 2024). "Bispecific antibodies that simultaneously target PD1 and other inhibitory receptors like TIGIT, TIM3, or LAG3 are designed to reinvigorate these exhausted T cells, potentially restoring their anti-tumor functionality." (PMID 39591972, 2024). "In certain malignancies, the simultaneous expression of LAG-3 and PD-1 on TILs is associated with impaired CD8+ effector T-cell function, contributing to tumor immune evasion." (PMID 38474377, 2024). "Since both Lag-3 and PD-1 are co-expressed on tumor-infiltrated T cells, the cocktail of aLag-3 and aPD-1 functioned to reduce tumor size more effectively than each treatment alone in preclinical model systems." (PMID 39234253, 2024). "LAG-3 has been shown to be an important inhibitory pathway involved in tumor development, along with other inhibitory checkpoints." (PMID 39796650, 2024). "Targeting LAG-3 and its ligands is one of the effective therapies to enhance anti-tumor immune responses and inhibit tumor growth." (PMID 39660130, 2024). "Gal-3 is a galactose-binding lectin secreted by tumor cells whose interaction with LAG3 was reported to suppress CD8+ T cell function." (PMID 38556085, 2024). "LAG-3 interacts with a variety of other immune cells, including dendritic cells (DCs) and natural killer (NK) cells, to regulate tumor immune response." (PMID 39252941, 2024). "Cluster 3 expressed higher levels of Itgae (CD103) and Cluster 5 higher levels of Lag3, suggesting that these represent distinct memory populations in the tumor immune environment and they appear to be less depleted by radiation." (PMID 38789721, 2024). "FGL1 is positively correlated with Treg and MDSC populations, as determined by analysis of the TIMER database, suggesting the regulatory effect of FGL1/LAG-3 signaling on immunosuppressive cells in the tumor microenvironment." (PMID 38973608, 2024). "NK cell “exhaustion” is also associated with a concomitant increase in markers like PD-1, TIGIT, TIM-3, LAG-3, etc., which has been observed in cancer patients and tumor microenvironment-derived NK cells." (PMID 39768300, 2024). "Before euthanasia, the protein level was restored in the RaST group, demonstrating that the inhibitory role of LAG-3 accelerated tumor progression and subsequent death of these mice." (PMID 38558990, 2024). "Targeting LAG-3/Gal-3 therapy overcomes immunosuppression and enhances anti-tumor response in endometrial cancer, multiple myeloma, and vulvar squamous neoplasia." (PMID 39252941, 2024). "While the T/DC, T/M2_1, and T/M2_2 communities contained most of the CD8+ T cells in the tumor tissue, these cells expressed significant levels of potential exhaustion markers such as PD-1 and LAG-3." (PMID 39485838, 2024). "In cancer, a small population of CD4+CD25hiFOXP3+ Tregs expressing LAG-3 is preferentially expanded in the PBMCs of cancer patients compared to healthy controls as well as within the tumor bulk itself." (PMID 39346924, 2024). "In this study, we observed higher expression levels of LAG-3 compared to those of other molecules in the tumor center and periphery in both the MSI-H and MSS groups." (PMID 38672108, 2024). "Along with relatlimab, LAG-3 inhibitor fianlimab has shown encouraging results in bolstering cytotoxic T-cell-mediated tumor cell lysis." (PMID 38342925, 2024). "Our analysis showed that LAG3 was upregulated in tumor tissues, especially in late-staged, high-grade KIRC." (PMID 38277212, 2024). "Spatial mapping further associates low MC tumor regions with immune escape, mediated by PDGFRB signaling activating the downstream immunosuppressive LAG3/FGL1 axis." (PMID 39015573, 2024). "Its efficacy hinges on simultaneous engagement of LAG-3 and PD-L1, facilitating effective T cell-tumor cell interactions." (PMID 38475778, 2024).